ENSG00000238966
Synonyms: LOC124900271
Gene: Small nucleolar RNA gene on chromosome 8 (42,043,504 to 42,043,575, reverse strand). Ensembl gene ENSG00000238966.
Gene Ontology:
Biological process: RNA processing
Cellular component: nucleolus
Homologues: Paralogues in human: SNORD112 (81% identical).